HBA1 (hemoglobin subunit alpha 1)
Diseases named in the same sentence as HBA1 in open-access papers (continued):
Sharing a sentence is not in itself a finding about the gene and the disease.
Alpha-thalassemia (24 papers, 2012 to 2025). Alpha-thalassemia is an inherited hemoglobinopathy characterized by impaired synthesis of alpha-globin chains leading to a variable clinical picture depending on the number of affected alleles. "In alpha-thalassemia, the common mutation types are often deletions affecting one or more of the alpha-globin genes (HBA1 and HBA2) or one pseudogene with a homozygous configuration of the allele, which results in the hydrops fetalis form." (PMID 40523316, 2025). "A lower MCHC is associated with alpha thalassaemia, resulting from deletions in HBA1 and HBA2 genes." (PMID 40446072, 2025). "Similarly, 5 major haplotypes are identified in HBA1/HBA2 homologous region while one of them is found highly linked with deletional α‐thalassemia mutations." (PMID 39737841, 2025). "Second is theco-inheritance of alpha globin locus defect, either an alpha-thalassemia deletion(α-thal) which is often observed in β-thal patients, resulting as a positivemodifier or, conversely, the presence of additional copies of HBA2or HBA1 genes which causes a more severe form of β-thal." (PMID 32142096, 2020). "The deletion HBA2 gene would have greater impact in the generation of the alpha-thalassemia phenotype, in comparison to deletion HBA1." (PMID 41262547, 2025). "For instance, in the case of alpha thalassemia, the highly homologous sequences between HBA1 (NM_000558.5) and HBA2 (NM_000517), pose challenges in accurate identification." (PMID 38982507, 2024). "On the other hand, alpha thalassemia is mainly attributed to deletions in the alpha hemoglobin locus 1 (HBA1) (OMIM *141800) or alpha hemoglobin locus 2 (HBA2) (OMIM *141850)." (PMID 38535125, 2024). "Subsequent NGS analysis uncovered a whole-gene deletion of HBA1 and HBA2, alongside an LP/P variant in PIEZO1, leading to a conclusive diagnosis of alpha thalassemia minor combined with dehydrated hereditary stomatocytosis." (PMID 37697358, 2023). "If both Hba1 and Hba2 genes were affected by the Cre/lox recombination, severe alpha thalassemia would be induced, resulting in embryonic lethality." (PMID 36302779, 2022). "Deletion at 16p13.3 includes the loss of multiple genes including HBA1 and HBA2 resulting in alpha thalassemia phenotype, however the genes responsible for ID and other development abnormalities are not yet clearly identified." (PMID 28935972, 2017). "A similar scenario has been put forward for rearrangements associated with the alpha-globin gene family, where recurrent deletions of HBA1 and HBA2 associated with alpha-thalassemia have reached a high frequency in Mediterranean and Pacific populations." (PMID 23594316, 2013). "HBA1/HBA2‐genotyping was performed in 207 children (53%), and α‐thalassemia was diagnosed in 47 children (23%) with −α3.7/αα being the predominant genotype (13%)." (PMID 36819175, 2023). "The alpha-thalassemia (alpha-thal) is the most common genetic disorder in the human population and is caused by the decreased or absent synthesis of the alpha globin chain due to the deletion or nondeletion mutation of one or both alpha-globin genes (HBA1 and HBA2), located on chromosome 16." (PMID 23316245, 2012). "However, due to the identical length of the HBA1 and HBA2 genes, sequencing analysis for alpha-thalassemia has been challenging." (PMID 40523316, 2025).
Hypertension (11 papers, 2016 to 2025). The presence of chronic increased pressure in the systemic arterial system. "Furthermore, higher baseline HbA1 values were associated with increased risk of hypertension during long-term follow-up." (PMID 26759608, 2016). "HBA2 and HBA1 have a key role in hypertension, but these genes might be linked with development HF." (PMID 34218797, 2021). "The obesity-related hypertensive patients had a higher level of DBP, weight, WC, FBG, HbA1, TC, TG, LDL-C, and SUA and had lower level of age and HDL-C (all P < 0.0001)." (PMID 36504973, 2022). "One RCT used rehab videos (Movies4Stroke) with reminders and had no significant change in control of hypertension, LDL, or HbA1." (PMID 36694257, 2023).
anemia (10 papers, 2019 to 2024). A reduction in the number of red blood cells, the amount of hemoglobin, and/or the volume of packed red blood cells. "We discovered rare deletions in HBA1/HBA2/HBB associated with anemia." (PMID 34764282, 2021). "We discover rare deletions in HBA1/HBA2/HBB associated with anemia." (PMID 34764282, 2021). "There were no changes in erythrocyte hemoglobin protein, erythrocyte size, or erythrocyte volume upon Cdh5-Cre–driven deletion; this is in contrast to the decreased erythrocyte volume and anemia in Hba1 global knockout animals (Hba1–/–)." (PMID 36302779, 2022). "Additionally, in the global Hba1–/– genotype, the distance to exhaustion was also decreased, although this was confounded by the anemia in those mice." (PMID 36302779, 2022). "Thus, the low expressed level of HBA1, HBA, and HBB along with inflammation may indicate anemia of inflammation in infected cattle (BRD susceptible cattle)." (PMID 36579334, 2022). "We further analyzed HBA1 and FGA abundance levels in the peripheral blood as markers for anemia and thromboembolic disease, respectively." (PMID 36759757, 2023). "Although we excluded the patients who had severe anemia, which could influence HbA1 levels, we did not exclude the patients with conditions such as hypothyroidism, liver dysfunction, and malnutrition, which can influence GA levels." (PMID 39007025, 2024).
hemoglobinopathies (8 papers, 2021 to 2026). "NM_000558.5) was detected in the HBA1 gene, in heterozygosity, during a routinely performed population screening for haemoglobinopathies." (PMID 41874100, 2026). "The main purpose of this study is to compare the performance of various in silico predictors and determine the most appropriate ones for predicting the functional impact of short nucleotide variants (SNVs) in HBA1, HBA2, and HBB related to haemoglobinopathies." (PMID 36453528, 2022). "As a result of limited diagnostic potential using high-performance liquid chromatography (HPLC), as it may not detect high oxygen affinity hemoglobinopathies, our NGS panel includes mutations in α- or β-globin genes (HBB, HBA1, HBA2) and the use of HPLC is not part of our algorithm." (PMID 35743463, 2022).
Insulin resistance (8 papers, 2021 to 2024). Increased resistance towards insulin, that is, diminished effectiveness of insulin in reducing blood glucose levels. "Biomarkers of insulin resistance such as serum HbA1 level were suggested as remarkably positively associated with chronic pain and were even suggested as effective biomarkers in differentiating and classifying individuals with chronic pain among a control group." (PMID 38610920, 2024). "Despite intensive screening, we had a shortfall of individuals meeting both the inclusion criteria of insulin resistance and increased HbA1 c." (PMID 39274338, 2024). "Treatment of diabetic rats with MLT significantly normalized the levels of serum glucose, HbA1-c, and the lipid profile and improved the insulin levels and insulin resistance compared with diabetic rats, affirming its antidiabetic effect." (PMID 33748504, 2021). "Some studies suggest that LSD or SSD can lead to impaired fasting blood glucose, abnormal HbA1, and insulin resistance." (PMID 33834077, 2021). "These included glycated haemoglobin (HbA1), fasting blood glucose (FBG), post-prandial blood glucose, fasting insulin, postprandial insulin, and the homeostasis model-insulin resistance (HOMA-IR)." (PMID 35270573, 2022). "Systemic insulin resistance indicators, including serum fasting blood glucose (FBG), fasting insulin (FINS), Homeostatic Model Assessment for Insulin Resistance (HOMA-IR), and hemoglobin A1 (HbA1), were upregulated by the PM2.5 instillation." (PMID 34745386, 2021). "Systemic insulin resistance indicators, including FBG, FINS, HOMA-IR, and HbA1, were upregulated as the PM2.5 instillation concentration was increased." (PMID 34745386, 2021). "Systemic insulin resistance indicators, including serum fasting blood glucose (FBG), fasting insulin (FINS), Homeostatic Model Assessment for Insulin Resistance (HOMA-IR), and hemoglobin A1 (HbA1), were examined." (PMID 34745386, 2021).
malaria (8 papers, 2013 to 2023). Malaria is a serious and sometimes fatal disease caused by a parasite that commonly infects a certain type of mosquito which feeds on humans. "Malaria is one pathogen that drives HBA1 variation, although alternative telomere maintenance in cancer cells through enhanced recombination of chromosomal ends proves another example of how effective this mechanism can be in generating diversity." (PMID 37164635, 2023). "The α–thalassaemia trait (α+–thalassaemia or −α/−α), is known to protect against severe malaria and like HBB-βS, is thus highly prevalent in malaria endemic areas, particularly the 3·7 kb alpha-globin gene (HBA1/HBA2) deletion in Africa." (PMID 33461216, 2021). "Variants in genes residing at these three loci (HBB, HBA1/HBA2, and G6PD) confer resistance to malaria in Africans." (PMID 23696099, 2013). "Three loci previously associated with resistance to malaria—HBB (11p15.4), HBA1/HBA2 (16p13.3), and G6PD (Xq28)—were associated (P ≤ 1 × 10−6) with RBC traits in the discovery cohort." (PMID 23696099, 2013). "Variants in genes residing in these loci (i.e., HBB, HBA1/HBA2, and G6PD) confer resistance to malaria." (PMID 23696099, 2013). "This increased the strength of the evidence that HBB, ABO, HBA1-2, and FREM3/GYP are associated with protection against severe malaria compared with the non-weighted case–controls odds-ratios (for HBA1-2: p = 10−5 versus p = 10−4; ABO: p = 10−13 versus p = 10−8; FREM3: p = 10−12 versus p = 10−11)." (PMID 35676275, 2022). "In this study, we identified genes related to the malaria resistance pathway (KEGG: hsa05144), including CCL2, CD40, HBA1, and HBA2 as the differential genes in DAI, indicating different selective pressure posed by malaria on the DAI compared to other M.Yunnan.West." (PMID 35864541, 2022).
COVID-19 (4 papers, 2021 to 2025). A disease caused by infection with severe acute respiratory syndrome coronavirus 2. "These proteins either act as positive regulators of cell death (HBG1, HBB, HBD, and HBA1) or are involved in the cellular response to tumor necrosis factor (FABP4, GPD1, THBS1, ASS1, and PCK2), suggesting that apoptosis may be an important cause of heart failure in patients with COVID-19." (PMID 38087340, 2023). "Furthermore, proteomic analysis of airway mucus from severe COVID-19 patients revealed variations in the expression of HBB and HBA1 proteins." (PMID 39358504, 2025). "The COVID-19 convalescents had significantly elevated immunoglobulins, Orosomucoid 2 (ORM2), peroxiredoxin-2 (PRDX2), hemoglobin subunits (HBD, HBB and HBA1), as well as proteins involved in cholesterol transport such as cholesteryl ester transfer protein (CETP) and apolipoprotein A1 (APOA1)." (PMID 38396092, 2024). "In comparison, clusters D and E had proteins with higher levels in COVID-19 convalescents, e.g. immunoglobulins playing a role in antigen recognition (e.g. IGKV1-27, IGKV1-39, IGHV1-46, IGLV3-1, and PRDX2), hemoglobin subunits (e.g. HBB, HBA1, and HBD), and carbonic anhydrase (CA1)." (PMID 38396092, 2024).
erythrocytosis (4 papers, 2021 to 2023). "Up to now, two types of erythrocytosis have been associated with mutations in hemoglobin genes, HBA1, HBA2 (ECYT7) and HBB (ECYT6) respectively, however hemoglobin variants do have diverse pathophysiology." (PMID 34440324, 2021). "The mutations K144N (Hb Andrew-Minneapolis) in HBB and K139E (Hb Hanamaki) in HBA1 also produce erythrocytosis." (PMID 36830724, 2023). "We sequenced the HBB, HBA1 and HBA2 genes of 75 patients with idiopathic erythrocytosis." (PMID 35052472, 2022). "Therefore, we recommend the systematic sequencing of the HBB, HBA1 and HBA2 genes in the exploration of idiopathic erythrocytosis." (PMID 35052472, 2022). "The HBB, HBA1 and HBA2 genes were not part of our initial NGS panel since in our initial diagnostic strategy, blood gases were performed as part of the screening workup for erythrocytosis." (PMID 35052472, 2022).
lung carcinoma (4 papers, 2016 to 2023). "Hemoglobin alpha 1 globin chain (HBA1), identified in our study, was recently shown to be expressed in lung cancer tissues and in the exhaled breath condensate of lung cancer patients." (PMID 35512017, 2022).
type 2 diabetes (4 papers, 2013 to 2024). "Although three patients developed type 2 diabetes during the 6 months of treatment, they showed normal levels of glycosylated HbA1 at 1 year with diet therapy alone." (PMID 23224025, 2013). "Thus, the study participants’ average baseline age, year of duration of type II diabetes, Glycosylated hemoglobin (HbA1-c), gender( male and female), blood pressure(systolic and diastolic), body weight, and body mass index were assessed in the four allocated groups." (PMID 36224647, 2022).
adenoma (3 papers, 2007 to 2022). A neoplasm arising from the epithelium. "Our study resulted in the identification of novel protein biomarker panels with higher sensitivities for high‐risk adenomas and CRCs than HBA1, which have plausible roles in colorectal carcinogenesis." (PMID 31784980, 2020). "Still, the newly established panels performed better for the detection of CRC and adenomas than the HBA1 protein in this study, which is currently used for FIT test." (PMID 36369736, 2022). "Meanwhile, hemoglobin (HBA1, HBB or HBD) was not significantly differential between high‐risk adenomas and controls, and subsequently it was not selected in any of the biomarker panels, which is in line with the limited sensitivity of FIT for adenomas." (PMID 31784980, 2020).
gastric cancer (3 papers, 2022 to 2024). A primary or metastatic malignant neoplasm involving the stomach. "Moreover, TRIM62, MET, and HBA1, which were significantly associated with oxidative stress, may be biomarkers for the prognosis of gastric cancer." (PMID 35659682, 2022). "Research has shown that oxidative stress is increased in T cells and decreased in mucous cells in the gastric cancer microenvironment, while TRIM62, MET and HBA1, which are associated with oxidative stress, may be biomarkers reflecting the prognosis of gastric cancer." (PMID 36439106, 2022). "Recent single cell RNA-sequencing analysis of gastric cancers shows that HBA1 is overexpressed in gastric cancer cells." (PMID 38492056, 2024). "The genes MET and HBA1, which were significantly related to oxidative stress, were extracted from mucous cells, and their expression significantly affected the survival and prognosis of gastric cancer patients." (PMID 35659682, 2022). "Our analysis also provides potential biomarkers for prognostic survival analysis of gastric cancer related to oxidative stress: TRIM62, MET, and HBA1." (PMID 35659682, 2022).
Hyperglycemia (3 papers, 2016 to 2024). An increased concentration of glucose in the blood. "TG (rs2275737) ADIPOR1 gene genotype carriers were found to have the highest levels of glycosylated hemoglobin (HbA1), whereas TT (rs2275738) caused stable hyperglycemia." (PMID 35366291, 2022). "Moreover, there is an association of high HbA1 levels with hyperglycemia, dyslipidemia and hyperinsulinemia, which mediates vascular dysfunction, activation of the renin-angiotensin-aldosterone system, sympathetic nervous system, and possibly negative alterations in BP." (PMID 26759608, 2016). "Nevertheless, hyperglycemia (evaluated by HbA1) that is intimately related with glycemic control, plays an important role in the development of microvascular complications." (PMID 26759608, 2016). "The general metabolic profile of children with type 1 diabetes agrees with the biological changes in characteristics of ketoacidosis, the average values showing hyperglycemia 385.94 ± 168.27 mg/dL, increased HbA1 12.37 ± 2.24%, low alkaline reserve 13.09 ± 7.31, and acidosis 7.17 ± 0.34." (PMID 39457127, 2024).
Obesity (3 papers, 2021 to 2024). Accumulation of substantial excess body fat. "In this regard, HBA1 and HBB were found to be decreased in serum proteome of metabolically abnormal individuals with obesity compared to controls." (PMID 38703299, 2024).
type 1 diabetes (3 papers, 2022 to 2024). "The most closely related study was carried out with adolescents diagnosed with type 1 diabetes, in whom higher EE values were associated with higher levels of HbA1, total cholesterol and LDL-c, which are risk factor of MS." (PMID 37789897, 2023). "In one case report, the cIMR in a 12-year-old boy with type 1 diabetes diminished during consequent blood glucose control from 0.048 mm to 0.036 mm (initial HbA1 c level: 15%; after 41 months: 8.2%)." (PMID 35268268, 2022).
bladder cancer (2 papers, 2023). "Additionally, two proteins (HBB and HBA1) were differentially expressed between bladder cancer patients with a recurrent diagnosis vs. tumor-free samples of bladder cancer patients, but their biological relevance is very limited." (PMID 37371512, 2023). "Notably, the expression of HBA1 and HBB is significantly higher in cervical and bladder cancer tissues than in normal cervix tissues." (PMID 38067210, 2023). "In the second biomarker discovery study to detect a biomarker panel to monitor bladder cancer patients in follow-up, only HBB and HBA1 were identified as statistically significant biomarkers with an absolute fold change larger than 0.6 and an FDR-corrected p value smaller than 0.05." (PMID 37371512, 2023). "HBA1 and HBB were the only statistically significant biomarkers with an absolute fold change larger than 0.6 and an FDR-corrected p value smaller than 0.05 in the other biomarker discovery study with bladder cancer patients with a recurrence diagnosis and tumor-free patients in follow up." (PMID 37371512, 2023).
breast cancer (2 papers, 2023 to 2024). A primary or metastatic malignant neoplasm involving the breast. "Hemoglobin subunit alpha 1 (A0A5B8JID5) was found with an AUC > 0.80 in the ROC curve and was in lower abundance in the bitches with mammary tumors in our study." (PMID 39057100, 2024). "Moreover, CTCs exhibited higher expression of HBA1/2, which is consistent with our finding that ectopic expression of the AST factors induced HBA1/2 in AST cells and with recent reports showing that hemoglobin facilitates breast cancer CTCs to suppress anoikis and form distant metastases." (PMID 36991428, 2023).
dementia (2 papers, 2023 to 2025). Loss of intellectual abilities interfering with an individual's social and occupational functions. "In parallel, it has also been reported that metformin cessation might increase the incidence of dementia, independently of changes in HbA1 levels or use of insulin in a large study including race as covariable." (PMID 41146261, 2025).
hydrops fetalis (2 papers, 2024 to 2025). Hydrops fetalis is a severe and challenging fetal condition usually defined as the excessive accumulation of fetal fluid within the fetal extravascular compartments and body cavities that manifests as edema, pleural and pericardial effusion and ascites. "No PCR product from the HBA2 and HBA1 genes was obtained from the Bart’s hydrops fetalis (--SEA/--SEA) sample." (PMID 38961367, 2024).
ovarian carcinoma (2 papers, 2020 to 2023). A malignant neoplasm originating from the surface ovarian epithelium. "A recent study has shown that hemoglobin subunit alpha 1 (HBA1) and hemoglobin subunit beta (HBB) levels were significantly elevated in patients with ovarian cancer compared to healthy patients." (PMID 38067210, 2023). "In ovarian cancer, HBB and HBA1 are downregulated by at least ten folds when compared to normal ovarian tissues." (PMID 32695162, 2020).